CCND1 (cyclin D1)
Diseases named in the same sentence as CCND1 in open-access papers (continued):
Sharing a sentence is not in itself a finding about the gene and the disease.
ependymoma (7 papers, 2017 to 2022). A WHO grade II, slow growing tumor of children and young adults, usually located intraventricularly. "Previous studies have shown that cyclin D1 overexpression is associated with a poor prognosis and recurrence in supratentorial ependymomas." (PMID 33271970, 2020). "According to the microarray analysis, CCND1 is up-regulated in supratentorial and infratentorial ependymomas and is associated with DNA repair." (PMID 29416789, 2018). "Indeed, immunohistochemical expression of cyclin D1 is associated with worse progression-free survival in ependymoma." (PMID 35204045, 2022). "To confirm whether CCND1 were associated with DNA repair in ependymomas, we checked the expression level of CCND1 using qRT-PCR and IHC staining firstly." (PMID 29416789, 2018). "To identify whether CCND1 causes radio-resistance in ependymomas, we knocked down CCND1 expression and quantified the corresponding cell viability after treatment with radiation." (PMID 29416789, 2018). "The survival trend indicated that CCND1 might cause malignancy in ependymomas." (PMID 31324163, 2019). "We investigated the immunohistochemical expression of p27 and p57 in ependymoma, with a secondary emphasis on cyclin D1, nestin, and Ki-67." (PMID 35204045, 2022). "We investigated the immunohistochemical expression of p27 and p57 in 65 cases of ependymoma, with a secondary emphasis on cyclin D1, nestin, and Ki-67." (PMID 35204045, 2022). "Though cyclin D1, nestin, and Ki-67 are well-studied in ependymoma, data from additional cohorts are needed." (PMID 35204045, 2022). "Cyclin D1, nestin, and Ki-67 are useful markers in ependymoma, but evidence-based cutoff values are required to standardize interpretation." (PMID 35204045, 2022). "Cyclin D1, nestin, and Ki-67 are useful markers in ependymoma, but evidence-based cutoff values are required to standardize this interpretation." (PMID 35204045, 2022). "The array hybridization intensity showed that CDK4 and CCND1 are significantly upregulated in supratentorial and posterior fossa ependymomas." (PMID 33271970, 2020). "In our earlier studies, we also identified incremental cyclin D1 expression in primary and recurring ependymomas and demonstrated that cyclin D1 regulates resistance to radiotherapy in ependymomas." (PMID 33271970, 2020). "In this study, integrated transcriptome analysis demonstrated that the cell cycle-related genes CDK4 and CCND1 are upregulated in ependymomas." (PMID 33271970, 2020). "In support of the strategy of targeting the CDK4/6–cyclin D1 complex for more effective treatment of ependymomas, a study demonstrated that abemaciclib, compared to other CDK4/6 inhibitors, has a higher efficiency in passively crossing the BBB." (PMID 33271970, 2020). "In the radiation-treated ependymomas cell model, CCND1 up-regulated after 6 and 8 Gy irradiation at 7 days." (PMID 29416789, 2018). "Knocking down CCND1 in ependymoma cells suppressed the activities of irradiation-induced homologous recombination and cell proliferation." (PMID 29416789, 2018). "Inducing DNA repair by upregulating CCND1 in our ependymoma cell model demonstrates a potential radio-resistance mechanism." (PMID 29416789, 2018). "In summary, the study highlights the limitations of current adjuvant therapies and the important role of CCND1 in ependymoma." (PMID 29416789, 2018). "Incremental expression of CCND1 in primary and recurrent ependymomas, especially on supratentotium, emphasizes the importance in tumor recurrence." (PMID 29416789, 2018). "We demonstrated that 24 primary and 16 recurrent ependymomas were up-regulated, and 5 out of 7 paired samples exhibited higher CCND1 expression in recurrent tumors." (PMID 29416789, 2018). "By analyzing high throughput gene expression microarray followed by qRT-PCR validation of ependymoma tissues, we proved CCND1 and RAD51 upregulation in both primary and recurrent ependymomas." (PMID 29416789, 2018).
ependymoma (continued). "In summary, these observations suggest a robust role of CCND1 in regulating cell proliferation and radio-resistance in ependymomas, providing a potential therapeutic target for pediatric ependymomas." (PMID 29416789, 2018). "To elucidate the role of CCND1, we knocked down CCND1 in two primary ependymoma cells and determined the proliferation by MTT assay." (PMID 29416789, 2018). "Therefore, we investigated the immunohistochemical expression of p27 and p57 in ependymoma, with a secondary emphasis on the expression of cyclin D1, nestin, and Ki-67." (PMID 35204045, 2022). "To verify whether CDK4 and CCND1 are overexpressed in ependymomas, we first checked the expression levels of CCND1 and CDK4 in the microarray dataset." (PMID 33271970, 2020). "By analyzing differential gene expression signatures between normal and tumor public ependymoma microarray datasets, we identified that most of the cell-cycle-associated genes are upregulated, and CDK4/6-cyclin D1 complexes are the major upstream regulators in the cell cycle process." (PMID 33271970, 2020). "Whole gene sequencing of ependymomas identified CCND1 amplifications in some cases." (PMID 31324163, 2019). "CCND1 expression showed upregulation after 7 days irradiation in ependymoma cells." (PMID 29416789, 2018). "We quantified CCND1 mRNA and protein level in seven paired samples (5 supratentorial and 2 infratentorial tumors, including pre-& post-RT ependymomas tissue due to relapse of the same case) and found higher CCND1 level in recurrent tumors from 3 supratentorial and 2 infratentorial tumors." (PMID 29416789, 2018). "The findings were concordant with the previous serial study in 149 adult and children ependymoma samples, which reported that the overexpression of CCND1 predominantly resided at supratentorial location and could predict the relapse in gross-total-resection cases." (PMID 29416789, 2018). "As gross total resection plays an important role in predicting PFS and OS, it is possible that CCND1 may play a more important mediator function in the residual ependymomas to facilitate DNA repair and promote residual tumor re-growth after the radiation treatment." (PMID 29416789, 2018). "CDK4, CCND1, and RB1 were found to be upstream regulators in the cell cycle process; therefore, CDK4 and CCND1 seem to be the main targets in ependymomas." (PMID 33271970, 2020). "By using integrated bioinformatics and through experimental validation, we found that at least one of the genes CCND1 and CDK4 is overexpressed in ependymomas." (PMID 33271970, 2020). "In this study, we validated the higher level of CCND1 and RAD51 in ependymoma especially the tumors located on supratentorium." (PMID 29416789, 2018). "We found that cyclin D1 was overexpressed in 20.0% of ependymomas; however, overexpression did not affect OS." (PMID 35204045, 2022). "We previously studied the differential miRNA expression of cyclin D1–positive and cyclin D1–negative ependymomas and found that cyclin D1–positive tumors underexpressed miRNAs with tumor suppressor activity." (PMID 35204045, 2022). "In further analyses, we found that the prognostic value of CCND1 amplifications in intracranial ependymomas was more distinct, although no statistical significance." (PMID 31324163, 2019). "However, the significance of CCND1 amplification in ependymomas is not yet well studied." (PMID 31324163, 2019).
fibrosarcoma (7 papers, 1997 to 2022). A malignant mesenchymal fibroblastic neoplasm affecting the soft tissue and bone. "AKAP12 sequestering of CCND1 and inhibition of CCND1 activity have been reported in parietal glomerular epithelial cells and in fibrosarcoma." (PMID 36193675, 2022). "Activated Stat1 have been reported to directly interact with cyclin D1 to promote its proteasomal degradation in fibrosarcoma cancer cells." (PMID 33046973, 2020). "To verify CCD-induced activation of cyclin D1 in vivo, we induced a fibrosarcoma in mice using methylcholanthrene (MCA), a potent chemical carcinogen, and exposed the mice to a chronic jet-lag schedule." (PMID 31039152, 2019). "For example, STAT1 specifically interacts with cyclin D1 and CDK4 to mediate cell cycle arrest in a human fibrosarcoma cell line after treatment with interferon (IFN)-γ." (PMID 28716119, 2017). "Western blot analysis using anti-human Rb antibodies and anti-human cyclin D1 antibodies in MCF-7 cells and high- and low-expression cyclin D1-transfected fibrosarcoma cells indicated that, after 6 h exposure, gossypol decreased the expression levels of these proteins in a dose-dependent manner." (PMID 9218727, 1997).
ischemia (7 papers, 2014 to 2024). A hypoperfusion of the BLOOD through an organ or tissue caused by a PATHOLOGIC CONSTRICTION or obstruction of its BLOOD VESSELS, or an absence of BLOOD CIRCULATION. "In mouse brains with transient focal ischemia, cyclin D1 protein is present in neurons within the infarcted region after ischemic insult, suggesting that its presence is associated with DNA fragmentation and is involved in neuronal death process." (PMID 34439951, 2021). "Our results indicated that Bach1 upregulation impaired the blood flow recovery from hindlimb ischemia and this effect was accompanied both by increases in ROS and cleaved caspase 3 levels and by declines in the expression of cyclin D1 in the injured tissues." (PMID 27057283, 2016). "On the other hand, other studies have reported that increased cyclin D1 expression is preferentially enhanced in the vulnerable CA1 of global ischemia-induced rats, and this cyclin D1 induction occurs in neurons before the appearance of chromosomal DNA fragmentation." (PMID 34439951, 2021). "However, we need to fully address whether IPC-mediated cyclin D1 expression contributes to neuroprotective effects against injury induced by ischemia and reperfusion." (PMID 34439951, 2021). "In this study, we examined changes in cyclin D1, cdk4, and related molecules in cells or neurons located in Cornu Ammonis 1 (CA1) of gerbil hippocampus after transient ischemia for 5 min (ischemia and reperfusion) and investigated the effects of IPC on these molecules after ischemia." (PMID 34439951, 2021).
myocardial infarction (7 papers, 2020 to 2023). Gross necrosis of the myocardium, as a result of interruption of the blood supply to the area, as in coronary thrombosis. "Increased expression of Cyclin D1 activates multiple cardiac proliferative pathways, promotes adult cardiomyocytes proliferation and preserves cardiac performance after myocardial infarction." (PMID 35087358, 2022). "CCND1 (Cyclin D1) has been reported to promote cardiomyocyte division in vivo and regulate cardiac function responding to heart failure in a rat myocardial infarction model." (PMID 32423033, 2020). "Overexpression of cell cycle-related gene regulators, such as Cyclin A2, Cyclin D1, and Cyclin D2, could enhance CM cell cycle activity and improve repair following myocardial infarction (MI) 4-6." (PMID 34646377, 2021).
Nephropathy (7 papers, 2013 to 2026). A nonspecific term referring to disease or damage of the kidneys. "Our study indicated that Shenhua Tablet is able to inhibit the abnormal proliferation of mesangial cells and to prevent kidney damage, which is likely associated with downregulation of p-Erk1/2 and reduced activity of its downstream target-cyclin D1." (PMID 26969153, 2016). "For example, cyclin D1 expression is decreased in cases of classic focal segmental glomerulosclerosis (FSGS), and increased in cases of HIV-associated nephropathy, chronic glomerulonephritis (CGN) and collapsing FSGS." (PMID 33686175, 2021). "In the model of mesangioproliferative nephritis (mesangioproliferative nephropathy (anti-Thy 1.1 nephritis model), the number of cyclin D1-positive podocytes was increased significantly." (PMID 27888806, 2016). "However, to our knowledge, no prior studies have shown CDKN2B or CCND1 eQTLs associating with kidney disease, as described in this manuscript." (PMID 35730565, 2022). "Like CCND1, CTNNB1 and ERBB2 are also involved in numerous cellular functions and kidney disease." (PMID 23637735, 2013).
retinoblastoma (7 papers, 2008 to 2024). A malignant tumor that originates in the nuclear layer of the retina. "A decrease in the level of murine cyclin D1 occurs in response to Rb family inactivation and this decrease may contribute to retinoblastoma suppression in mice through regulation of pocket protein activity." (PMID 18489754, 2008). "Whether upstream regulators of p107 and p130 activity such as cyclin D1, p27 and p19Ink4d can contribute to retinoblastoma in the context of p107 or p130 being intact will be important to elucidate." (PMID 18489754, 2008). "On the other hand, irradiation significantly increased the level of Cyclin D1, a cell cycle promoter that regulates cell cycle progression by phosphorylating CDK4/6 to inhibit retinoblastoma." (PMID 36092734, 2022). "As for CCND1 and CDKN1A, 3′ untranslated regions (UTRs) of both genes have sequences aligned with some of miR-17-92 clusters which is elevated in retinoblastoma." (PMID 25359779, 2014). "We found that the expression of Cyclin E and CDK2 was downregulated in retinoblastoma cells with TAZ knockdown, but no obvious changes were observed in Cyclin D1, CDK4 and CDK6 expression." (PMID 26464030, 2015).
serous carcinoma (7 papers, 2004 to 2025). "Low nuclear cyclin D1 showed a significant association with serous carcinoma (adjusted p value = 0.005) and a high tumour grade (adjusted p value < 0.0001)." (PMID 38612869, 2024). "BRCA1/2 alterations, PTEN loss, and gain of PIK3CA and CCND1 were characteristic for high-grade serous carcinomas." (PMID 33947352, 2021). "Postulated sensitivity to CDK4/6 inhibitor therapy was mostly due to CCND1 gain – particularly in patients with high-grade serous carcinomas- and CDKN2A loss." (PMID 33947352, 2021). "In serous carcinoma, high nuclear expression of CCND1 was detected in several samples, while other serous carcinoma cases showed low CCND1 expression." (PMID 39940659, 2025). "Studies have shown that Cyclin D1 is particularly overexpressed in complex hyperplasia and endometrioid carcinoma, whereas lower expression is more commonly associated with high-grade subtypes like serous carcinoma, which may follow alternative oncogenic pathways." (PMID 39940659, 2025). "These alterations were observed less frequently in endometrioid endometrial cancer compared to other subtypes, such as high-grade serous carcinomas, where CCND1 CNVs were significantly more common (p = 0.007)." (PMID 39940659, 2025). "Shi and colleagues also observed lower expression of cyclin D1 in serous carcinoma compared with mucinous and clear cell carcinoma subtypes." (PMID 29845750, 2018). "Weak cyclin D1 staining was observed in high‐grade serous carcinoma (P < .001), lymphatic vascular invasion (P = .026), bilateral involvement (P < .001), necrosis (P = .004), and patients with recurrence (P = .006)." (PMID 29845750, 2018). "Cyclin D1 overexpression is often observed in the early stages of endometrioid carcinoma and complex hyperplasia, marking potential early carcinogenic events, while lower expression levels are common in high-grade subtypes like serous carcinoma." (PMID 39940659, 2025). "In the current study, low nuclear cyclin D1 showed a significant association with serous carcinoma and a high tumour grade but did not influence survival." (PMID 38612869, 2024). "Although the LI for cyclin D1 appears to fall between borderline tumours and serous adenocarcinomas, this is not statistically significant (P=0.07) and the overall trend is towards an increase in expression by the Jonckheere–Terpstra test." (PMID 15083189, 2004).
urothelial carcinoma (7 papers, 2014 to 2025). A malignant neoplasm derived from the transitional epithelium of the urinary tract (urinary bladder, ureter, urethra, or renal pelvis). "Urothelial carcinoma had the highest number of CCND1 amplified tumors; accordingly we assessed mRNA levels in this histology type and observed significantly higher levels of CCND1 expression in urothelial cancer nonresponders (SD/PD) versus responders (PR/CR) (p = 1.5 × 10−2)." (PMID 33508232, 2021). "miR-34a negatively regulates the cell cycle by reducing CCND1 (cyclin D1) and CDK4 (cyclin dependent kinase 4) levels; its downregulation promotes a more aggressive behavior of FGFR3 in urothelial carcinoma cases." (PMID 29165379, 2017).
acute leukemia (6 papers, 2015 to 2023). A clonal (malignant) hematopoietic disorder with an acute onset, affecting the bone marrow and the peripheral blood. "Further study will be necessary to confirm whether there are other mechanisms involved in gal-3-mediated cyclin D1 expression other than Wnt signaling in the acute leukemia microenvironment." (PMID 25622682, 2015).
Alzheimer disease (6 papers, 2012 to 2024). A progressive, neurodegenerative disease characterized by loss of function and death of nerve cells in several areas of the brain leading to loss of cognitive function such as memory and language. "This may be relevant for the previously indicated involvement of cell cycle genes, as ectopic cyclin D1 expression was also observed in sites of neuronal cell death in Alzheimer's disease patients." (PMID 22741533, 2012).
brain cancer (6 papers, 2014 to 2023). A primary or metastatic malignant neoplasm affecting the brain. "PKM-mediated phosphorylation of histone H3 plays a critical role in the epidermal growth factor (EGF)-induced expression of cyclin D1 and c-Myc, which further promotes tumor cell proliferation in brain cancer." (PMID 37291128, 2023). "Overexpression of cyclin D1 has been described in a wide spectrum of human cancer types, such as breast, lung, liver and brain cancer." (PMID 24348867, 2014).
carcinoma in situ (6 papers, 2009 to 2024). "Overexpression of cyclin D1 in HNC is associated with the progression of dysplastic lesions into in situ carcinoma and poor clinical prognosis." (PMID 39123466, 2024). "Cyclin D1 was expressed in the basal and middle third of the epithelium in the low grade, and with full-thickness expression in high-grade dysplasia and carcinoma in situ." (PMID 35626215, 2022). "In support for this model, it has been shown previously that upregulation of cyclin D1 (CCND1) expression was detected in oral hyperplasia/premalignant lesions and CCND1 gene locus (11q13) amplification was found in early dysplasia, carcinoma in situ and also metastatic HNSCC." (PMID 19287496, 2009).